LCN2 (lipocalin 2)
Diseases named in the same sentence as LCN2 in open-access papers (continued):
Sharing a sentence is not in itself a finding about the gene and the disease.
Sepsis (continued). "While LCN2 deficiency has been shown to improve insulin resistance and diabetic encephalopathy, others have found that LCN2 (-/-) mice were more susceptible to HFD-induced obesity and LPS-induced sepsis, and one study has suggested that LCN2 deficiency plays only a minor role in mice fed with HFD." (PMID 34844610, 2021). "Previous studies have confirmed that CD47, Lcn2, and Sphk1 were involved in the sepsis process." (PMID 33204219, 2020). "Only two of these biomarkers seemed relevant to differentiate sepsis from plain infection (lipocalin 2 and MMP8), suggesting that neutrophil degranulation may be important in the pathogenesis of septic shock." (PMID 32073224, 2020). "Results showed hsa-miR-92a and lipocalin-2 could be used to distinguish sepsis-induced coagulopathy from sepsis-alone patients." (PMID 32075600, 2020). "Supporting the concept that Lcn-2 might correlate with recovery of patients during sepsis we aimed to determine if Lcn-2 expression holds predictive power for septic patients." (PMID 33065981, 2020). "The AUC analysis to assess biomarker sensitivity and specificity indicated that mid‐regional proadrenomedullin (MR‐ProADM) was the best biomarker for differentiating sepsis from infection, whereas lipocalin 2 in plasma was the best biomarker for distinguishing septic shock from sepsis." (PMID 32073224, 2020). "Furthermore, we showed that the antimicrobial protein Lcn2 was involved in the protective effect of flagellin; administration of Lcn2 even at 12 h after CPM treatment conferred protection to neutropenic sepsis model mice." (PMID 32365611, 2020). "In contrast, Lcn-2 should be beneficial in late-immune exhaustion phase of sepsis." (PMID 31514375, 2019). "In addition to its major role in maintaining local microbiota homeostasis and moderating systemic overactive immune response, Lcn2 has also been reported to protect the gut as well as the lungs, liver, and kidneys from organ failure in sepsis models." (PMID 31375129, 2019). "Indeed, the introduction of recombinant Lcn-2 attenuated LPS exhaustion and improved sepsis response of the FcGRIIb-/- lupus mice in the LPS pre-conditioning CLP model." (PMID 31514375, 2019). "We propose that development of a therapeutic strategy targeting lipocalin-2 could be highly promising in the management of gut-origin sepsis." (PMID 31375129, 2019). "Further research is warranted to comprehend the mechanism through which Lcn2 may harness the power of the host immune system to fight gut-origin sepsis, to provide bench side knowledge for bedside practice." (PMID 31375129, 2019). "Peripheral blood transcriptomics in humans have shown a parallel scenario since particular key mediators of the initial neutrophil response to infection, such as LCN2, BPI, CD24, CASP1 and MMP8, were strongly dysregulated in patients with sepsis-associated ARDS compared to sepsis patients." (PMID 31426444, 2019). "Moreover, a new neutrophil-related gene signature has been described in patients with early sepsis-induced ARDS, based on two anti-inflammatory genes: OLFM4 (encoding olfactomedin 4) and LCN2 (encoding lipocalin 2)." (PMID 27807817, 2016). "To evaluate whether the potentially beneficial effects of NGAL in-vivo have a significant impact on outcome during sepsis, we induced a highly lethal polymicrobial sepsis in mice and treated these with recombinant mouse Lipocalin-2 protein." (PMID 25893429, 2015). "The sepsis may have been determined by two factors – a well-developed iron uptake system by the bacteria that was competitive with the host, and the second factor, the low levels of Lcn-2 in the patients, which deprived the patients of protective function." (PMID 40569986, 2025). "Therefore, it is meaningful to verify the function of LCN2 in different sepsis models." (PMID 39512683, 2024). "In addition, LCN2 expression was also examined in the LPS-induced sepsis cell model." (PMID 39512683, 2024).
Sepsis (continued). "Additionally, we have found a clinical correlation between LCN2 and sepsis of intestinal origin." (PMID 38028617, 2023). "Hence, our findings offer new insights into the molecular mechanisms underlying COVID-19 and sepsis-induced ARDS and suggest CD3, CD247, CD2, CD40LG MMP-9, LCN2, and RETN as the potential targets for neutrophils in developing novel therapies and diagnostic tools for these diseases." (PMID 37822934, 2023). "Interestingly, we could also observe a devastating effect by LCN2 lower expression in IL-36R−/− mice in sepsis suggesting that LCN2 is one of the key factors driving IL-36-dependent lung injury." (PMID 38093296, 2023). "However, evidence have also shown that LCN2 may play a beneficial role in experimental autoimmune encephalomyelitis and sepsis models." (PMID 35413913, 2022). "Moreover, we could correlate FRA-1 expression to the expression of an essential anti-inflammatory molecule involved in sepsis response, Lipocalin 2 aka NGAL." (PMID 34712224, 2021). "Therefore, we hypothesized that both the cellular source of Lcn-2 as well as its iron-load crucially adds to its biological function during sepsis-induced renal injury." (PMID 33065981, 2020). "Our data indicates that Lcn2 could be an important player in the treatment of neutropenic sepsis." (PMID 32365611, 2020). "In addition, the presence or administration of Lcn2 induced hypoferremia of inflammation and upregulation of antioxidant enzymes (e.g., superoxide dismutase, heme oxygenase-1) in vivo, to limit iron-induced oxidative stress during sepsis." (PMID 31375129, 2019). "Accordingly, levels of serum Lcn-2 have been shown to be elevated in both classic inflammatory conditions such as colitis and sepsis and, moreover, in states of low-grade inflammation such as metabolic syndrome, demonstrating that serum Lcn-2 could serve as a marker of inflammation." (PMID 22957064, 2012). "In this study, we explored the involvement of LCN2 in SILI in cecal ligation and puncture (CLP)-induced sepsis model." (PMID 39512683, 2024). "Further ROC analysis suggested that the AUC of GCLM, LCN2, LTF, and CYP4V2 in diagnosis between severe forms and mild forms of sepsis were all >0.65." (PMID 36820206, 2023). "In sepsis, monocytes were negatively correlated with CD247, CD2, and CD40LG, while positively correlated with LCN2 and RETN." (PMID 37822934, 2023). "The genes TPSO, CYP1B1, LCN2, CLIC2, and ELL2 were up-regulated and FTO was down-regulated in sepsis compared to the uncomplicated infections (p < 0.05)." (PMID 36820206, 2023). "Drawing upon the insights gleaned from our murine sepsis-induced ARDS model and human subjects afflicted with sepsis-induced ARDS, we selected CD247, CD2, CD40LG, KLRB1, LCN2, and RETN as the foci of our subsequent investigation." (PMID 37822934, 2023). "In conclusion, the present study identified core immune‐related DEGs between severe burns and sepsis, including IL10, RETN, THBS1, FGF13, LCN2 and MMP9." (PMID 37060578, 2023). "Our findings revealed significant decreases in CD4, CD3e, IL-7R, CD5, CD247, CD2, CD40LG, ITK, and KLRB1, and significant elevations in MMP9, LCN2, and RETN in sepsis-induced ARDS compared to controls." (PMID 37822934, 2023). "In particular, the upregulation of MPO, MMP9, TLR2, and LCN2 in the lungs of sepsis-induced ARDS mice suggests their crucial role in developing lung injury in COVID-19 and sepsis." (PMID 37822934, 2023). "Of these, six hub genes (CD247, CD2, CD40LG, KLRB1, LCN2, RETN) showed significant alterations across COVID-19, sepsis, and geriatric sepsis-induced ARDS." (PMID 37822934, 2023). "By leveraging bioinformatics analysis and machine learning algorithms, we systematically identified five immune-related candidate hub genes (CLEC5A, KLRB1, LCN2, MCEMP1, and MMP9) and provided a nomogram for diagnosing ROP with sepsis." (PMID 38028617, 2023).
Sepsis (continued). "We further identified plasma proteins discriminating COVID-19 and sepsis, for example LBP, lactoferrin, and lipocalin 2; and differential pathways including neutrophil degranulation, complement, AP-1/p38MAPK, TLR, renin-angiotensin, and the HSC lineage." (PMID 35216673, 2022). "Under the neutropenic sepsis conditions induced by CPM treatment, hepatocytes should be the sole source of Lcn2 production." (PMID 32365611, 2020). "While TNF and LCN2 are dramatically upregulated in both ischemic and septic AKI, KIM-1 is induced primarily in ischemic injury and ICAM-1 in sepsis only." (PMID 32257978, 2020). "We showed that CPM treatment induced neutropenic sepsis in BL6 mice and demonstrated that Lcn2 extended the survival of neutropenic sepsis model mice." (PMID 32365611, 2020). "Differential analysis identified 6 proteins that were significantly upregulated in sepsis serum samples, including MMP9, lipocalin-2 (LCN2), serum amyloid A1 (SAA1), serum amyloid A2 (SAA2), paired-like homeobox 2B (PHOX2B), and lactoferrin (LTF) (|log2FC| > 1, P < 0.05)." (PMID 41306770, 2025). "Notably, the AUC of multiple markers (0.849) was significantly greater than those of LCN2, OLFM4, and miR-122-5p alone for 28-day mortality in patients with sepsis." (PMID 39901167, 2025). "Subsequently, based on an external validation cohort from our hospital, qRT-PCR demonstrated significant up-regulation on LTF, LCN2, ELANE, MPO, and CEACAM8 in peripheral blood of sepsis patients versus controls, thus further enhancing the reliability of the findings." (PMID 38912048, 2024). "In summary, our investigation conducted comprehensive bioinformatics analysis on two gene datasets (GSE28750 and GSE74224) and discerned LTF, LCN2, ELANE, MPO and CEACAM8 as key up-regulated genes in sepsis patients when compared with non-sepsis critically ill controls." (PMID 38912048, 2024). "Similarly, our investigation revealed that the expression levels of LTF and LCN2 were significantly increased in sepsis patients when compared with critical controls, implicating a potential link between LTF, LCN2 and sepsis." (PMID 38912048, 2024). "Additionally, when compared to sepsis shock, we found TPSO, GCLM, CYP1B1, LCN2, and LTF were up-regulated and the FTO and CYP4V2 were down-regulated in the sepsis (p < 0.05)." (PMID 36820206, 2023). "CD247, CD2, CD40LG, and KLRB1 displayed a positive correlation with CD8+ T cells and CD4+ T cells in both COVID-19 and sepsis cases, while LCN2 and RETN showed a negative correlation." (PMID 37822934, 2023). "Here, infected mice exhibit gene expression changes consistent with Gram-negative bacteremia and sepsis and Lcn2-/- mice are more likely to succumb to infection." (PMID 36054235, 2022). "Though the relationship of lipocalin-2 with sepsis and DIC has been studied, no study has yet evaluated its relationship with SIC." (PMID 32075600, 2020). "We used this dataset to analyze Lcn-2 expression in the whole blood transcriptome of survivors and non-survivors of sepsis." (PMID 33065981, 2020). "ROC curve analysis also suggested that LTF and LCN2 may serve as valuable biomarkers to differentiate sepsis patients from those with non-septic inflammatory conditions." (PMID 38912048, 2024). "LCN2 was positively correlated with neutrophils in COVID-19 but not in sepsis cases." (PMID 37822934, 2023). "Furthermore, LCN2 levels were significantly elevated during the acute phase of sepsis and showed a significant correlation with the D1 SOFA score, indicating its potential as a marker of sepsis severity." (PMID 37932342, 2023). "A total of 21 iron metabolism-related signatures were identified including 9 transporters, 8 enzymes, and 4 regulatory factors, among which LCN2 showed consistent differences between sepsis and healthy groups, sepsis and non-sepsis groups, and mild and severe forms of sepsis." (PMID 36820206, 2023).
Sepsis (continued). "Moreover, the decisive role of iron and/or Lcn-2-bound iron has not been elucidated in sepsis-induced kidney damage." (PMID 33065981, 2020). "In parallel, Lcn-2 in the WT mice might be already adequate to curb the less severe LPS exhaustion so the administration of rLcn-2 was not effective in sepsis attenuation in WT mice." (PMID 31514375, 2019). "Moreover, we found that CD3, CD247, CD2, and CD40LG were negatively correlated with KC, whereas MMP-9, LCN2, and RETN were positively correlated with KC, suggesting that these candidate hub genes may regulate geriatric sepsis-induced ARDS by modulating the recruitment of neutrophils to the lung." (PMID 37822934, 2023). "Known renal injury markers, such as markers Lcn2 (NGAL), Havcr1 (KIM1), Timp2, Igfbp7, are tubular injury markers and therefore are not indicative of the microvascular response in mouse CLP-sepsis." (PMID 40892345, 2025). "Further ROC analysis suggested the AUC of LCN2 and CYP1B1 in diagnosis between sepsis and uncomplicated infectious or noninfectious diseases were both >0.66." (PMID 36820206, 2023). "Plasma LCN2 also has a high sensitivity and a high negative predictive value for detection of AKI in adult sepsis patients." (PMID 36820206, 2023).
kidney damage (237 papers, 2010 to 2025). "Lipocalin-2 (LCN2) is a neutrophil gelatinase-associated lipocalin (NGAL) that has been suggested as a biomarker of kidney damage." (PMID 37746070, 2023). "Proteome profiler analysis of kidney lysates from young, old untreated and old treated mice also revealed that treatment with HK reverted the age-related increase of Pentraxin-2/SAP and Lipocalin-2/NGAL—two proteins associated with inflammation and kidney damage, respectively." (PMID 38951692, 2024). "We evaluated the expression of kidney damage‐related genes (Havcr1, Lcn2, and Spp1) and found that MHY5396 treatment significantly reduced their expression in the kidneys." (PMID 41159141, 2025). "Recent studies suggest that LCN2 is a reliable biomarker for microvascular complications, including diabetic retinopathy, nephropathy, and carotid atherosclerosis." (PMID 40137149, 2025). "An additional biomarker of kidney damage is lipocalin 2, another name for lipocalin-2 is neutrophil gelatinase-associated lipocalin (NGAL), a new 198-aminocytokine." (PMID 39065736, 2024). "Several other biomarkers were proposed for detecting kidney damage caused by OTA, such as lipocalin-2, tissue inhibitor of metalloproteinases-1 (Timp-1), clusterin, osteopontin, and vimentin, although KIM-1 was the most promising one." (PMID 37125184, 2023). "The high expression of LCN2 is significantly correlated with the clinical condition and pathological kidney damage in patients with LN, indicating that LCN2 is involved in the occurrence and development of LN and can be regarded as a potential biomarker." (PMID 37474625, 2023). "Urinary Lcn-2 has been proven to be a sensitive marker for kidney damage in acute and chronic kidney diseases." (PMID 23861783, 2013). "Elevated level of LCN2 in kidney is a well-recognized marker for both chronic kidney diseases, reflecting the extent of kidney damage." (PMID 22514649, 2012). "Similarly, lipocalin-2 has emerged as a promising marker for nephropathy, retinopathy, and neuropathy, potentially due to its role in oxidative stress and inflammation." (PMID 40137149, 2025). "However, LCN2 is usually released during bacterial infection to sequester iron and is recognized as a marker for kidney damage." (PMID 39598420, 2024). "Moreover, the present data disclosed that 5-FU induced obvious renal damage that was accompanied by upregulation of KIM 1 and lipocalin-2 genes, which confirmed kidney damage and kidney function alteration." (PMID 39065736, 2024). "Lipocalin-2 (LCN2), also known as neutrophil gelatinase-associated lipocalin (NGAL), is released by innate immune cells and can serve as an attractive biomarker of inflammation, ischemia, infection, and kidney damage." (PMID 37371057, 2023). "It has been documented that LCN2 is an iron-carrier protein, and its biological activity depends on its iron-load and on where it is produced (renal tubules or macrophages), which defines its dual role in the development of kidney damage." (PMID 35052623, 2022). "LCN2 levels persist during both acute and chronic phases of kidney damage, and may serve as a key propagating factor for chronic kidney disease." (PMID 22514649, 2012). "RT-qPCR detected elevated transcription levels of Lipocalin2 (LCN2; Lcn2) and Kidney injury molecule-1 (KIM-1;Havcr1) indicating kidney damage progressing over time." (PMID 39681572, 2024). "Thus, the therapeutic suppression of LCN2 may be useful to counteract kidney damage." (PMID 35966090, 2022). "Lipocalin 2 (LCN2) is a critical inflammatory mediator that is persistently induced during endotoxemia, reflecting the extent of kidney damage and kidney failure." (PMID 29285270, 2017). "We did not observe any upregulation of LCN2 expression; however upregulation of several other injury markers was observed in the absence of any histological evidence of kidney damage." (PMID 30608957, 2019).
kidney damage (continued). "Thus, studies with cystatin C (CisC), lipocalin-2 (NGAL), and microalbuminuria have shown that these are detected early during chronic kidney disease (CKD) diagnosis compared to seric creatinine and proteinuria, and indicate the location and severity of the kidney damage." (PMID 33061236, 2020).